EZH2 (enhancer of zeste 2 polycomb repressive complex 2 subunit)
Diseases named in the same sentence as EZH2 in open-access papers (continued):
Sharing a sentence is not in itself a finding about the gene and the disease.
B-cell lymphomas (continued). "Also, CPI-1205, an orally available selective inhibitor of EZH2, killed cells in both EZH2-WT and EZH2-mutant B-cell non-Hodgkin's lymphoma by altering PRC2 target gene expression in a dose- and time-dependent manner." (PMID 30984620, 2019). "EZH2 activation also represses the tumor-suppressive BLIMP1 in GC-B cell lymphoma." (PMID 31752930, 2019). "Indeed, early results with the EZH2 inhibitor EPZ6438 in patients with B-cell lymphomas and advanced solid tumours (NCT01897571) are encouraging." (PMID 30542123, 2018). "EZH2 inhibitors are currently being developed and clinical trials for B cell lymphoma are ongoing." (PMID 27502594, 2016). "Interestingly, a link between the miR-29 family by MYC has been recently reported, as repression of miR-29 by MYC through a corepressor complex with HDAC3 and EZH2 is observed in aggressive B-cell lymphomas." (PMID 26453442, 2015). "EZH2 is a critical oncogenic driver in germinal center-derived B-cell lymphomas." (PMID 25493630, 2014). "Intriguingly, Y641 mutant EZH2 detected in B-cell lymphoma is always heterozygous." (PMID 25520914, 2014). "Our results provide a basis for investigating whether GRag/EZH2 inhibitor combinations may have clinical utility in all germinal center derived B cell lymphomas." (PMID 25493630, 2014). "Mutational status of EZH2 and CD79B may vary in B-cell NHL samples over time and support the concept that individualized therapy should be based on molecular findings at the time of treatment, rather than on results obtained from previous specimens." (PMID 23361872, 2013). "Since EZH2 inhibition is already approved for the treatment of B cell lymphoma, we believe our study may provide new therapeutic avenues to investigate the efficacy of EZH2 inhibition as a strategy to re-sensitize myeloma cells to anti-CD38 MoAbs and overcome resistance." (PMID 37532787, 2023). "However, at least at the RNA level, we could not detect the altered expression of the major H3K27-HMT EZH1 and EZH2, which other studies have shown in force-stressed HPdLSCs and pathogenically stimulated human B cell lymphoma cells, such as BCBL1." (PMID 35326406, 2022). "Additionally, a recent study reported that another molecule, EPZ-011989, sharing a similar structure with EPZ-6438 could expand the inhibition range of EZH2 and improve pharmacodynamic and pharmacokinetic qualities in a mouse B cell lymphoma model." (PMID 28415635, 2017). "Also, EZH2, the major H3K27 methyltransferase, is mutated in certain B cell lymphomas." (PMID 24097438, 2014). "The efficacies of the EZH2 inhibitors EPZ-6438 (also known as Tazemetostat) and GSK126 against various cancers, including B-cell lymphoma, have been tested in clinical trials." (PMID 33436557, 2021). "This study reveals one possible molecular mechanism how B-cell lymphomas can acquire resistance to DZNep, and proposes AHCY as a potential biomarker for investigation during the administration of EZH2-targeted therapy with DZNep." (PMID 32408898, 2020). "Another inhibitor CPI-1205, disturbing the interaction of EZH2 with PRC2 complex, is currently evaluated in a phase 1 clinical trial in patients with B-cell lymphomas (NCT02395601)." (PMID 29556394, 2018). "In 2015,the selective and orally available EZH2 inhibitor, EPZ011989, was also reported and shown to have significant effects in the mouse xenograft model of B cell lymphoma." (PMID 29556394, 2018). "Recently, miRNA-494 was reported to be a part of a regulatory loop between EZH2 and c-MYC in B-cell lymphoma." (PMID 28052011, 2017). "It has been previously shown that a combination of a different EZH2 inhibitor, EPZ-6438, was synergistic with glucocorticoid receptor agonists such as prednisolone and dexamethasone in B cell lymphoma." (PMID 27449082, 2016). "In aggressive B cell lymphoma, miR-29a is repressed by MYC within a co-repressor complex that also includes HDAC3 and EZH2." (PMID 24348513, 2013).
B-cell lymphomas (continued). "MYD88 mutations did not co-occur with EZH2 or TNFRSF14 mutations, which are mostly found in B-cell lymphomas of the germinal center as opposed to the activated B-cell lymphomas, in which MYD88 is commonly mutated." (PMID 40511879, 2025). "The experimental findings suggest that novel EZH2 inhibitors, like ribavirin and IHMT-EZH2-115, may hold promise against B-cell lymphomas." (PMID 40299416, 2025). "Moreover, we have proven that pharmacological EZH2 inhibition by SAM-competitive small molecule drugs increase oxaliplatin resistance drastically in mature T-cell lymphoma, T-cell leukemia, and B-cell lymphoma cell lines." (PMID 37297005, 2023). "At the 2022 national meeting of the Italian Society of Experimental Hematology, our group presented a new kind of “higher order multiplexing ddPCR” able to simultaneously measure the expression of BMI1, EZH2, USP22 and GAPDH genes in 56 patients affected by aggressive B-cell lymphoma (DLBCL)." (PMID 35741115, 2022). "Later studies uncovered that Astemizole could disrupt EZH2-EED interaction and arrest cell proliferation in some B cell lymphoma cell lines." (PMID 31752930, 2019). "In view of the abundantly present epigenetic abnormalities of H3K27 tri-methylation and histone acetylation, a couple of studies have combined EZH2 inhibitors with different HDAC inhibitors for the treatment in MM and B cell lymphoma cells, and favorable therapeutic coordination were observed." (PMID 31752930, 2019). "A phase I/II multicenter clinical trial on the use of an EZH2 inhibitor as monotherapy (E7438 or Tazemetostat) in patients with B-cell lymphoma (GCB and non-GCB DLBCL and grade 3 FL) or with advanced solid cancers is currently ongoing (NCT01897571)." (PMID 26497210, 2016). "EZH2 has been actively targeted for various cancers, with EPZ-6438 as the most advanced (in phase I or II clinical trials for non-Hodgkin's lymphoma, B-cell lymphoma, synovial sarcoma, renal, soft tissue sarcoma, breast and mesothelioma cancers) among all currently active cancer drug programs." (PMID 27889707, 2016). "Finally, CPI-1205 selectively inhibits the interaction of EZH2 with PRC2 complex and is currently evaluated in a phase 1 clinical trial in patients with B-cell lymphomas (NCT02395601)." (PMID 27793053, 2016). "EPZ-6438 also eliminates the growth of several EZH2 mutant xenografts including WSU-DLCL2 (Y641F), Pfeiffer (A677G), KARPAS-422 (Y641N) etc., and has been approved for human clinical trials in patients with advanced solid tumors or with B-cell lymphoma." (PMID 25520914, 2014). "Interestingly, previous reports suggest a potential cooperativity between BCL6 and chromatin-modifying proteins such as EZH2, LSD1, and the NCOR/HDAC3 complex, suggesting that BCL6 may act as an epigenetic re-programming TF in cancers such as B-cell lymphoma." (PMID 35711675, 2022). "Considering that EZH2 is involved in STK39 regulation and considering that a recent study showed STK39 to be repressed by DNA hypermethylation in B cell lymphoma, we assessed whether DNA methyltransferases were involved in the EBNA3A-mediated silencing of STK39 in LCLs." (PMID 29367247, 2018). "In previous studies on HDAC inhibitors in B-cell lymphoma, alterations in H3K27me3 levels post-HDAC inhibitor treatment were not significant, which may explain the limited exploration of the combined mechanisms of HDAC inhibitors and EZH2 inhibitors from the perspective of H3K27me3 modifications." (PMID 40659662, 2025). "Mutations in the SET domain of the EZH2 gene that increased its tri-methylation activity are prevalent in other B cell lymphoma but have not been reported in the case of MCL, suggesting that high EZH2 expression in MCL is sufficient for augmenting oncogenic signaling." (PMID 37626420, 2023).
diffuse large B-cell lymphoma (127 papers, 2011 to 2025). "For diffuse large B cell lymphomas cells with EZH2 gain-of-function mutations that are resistant to EZH2 inhibitor treatment alone, combined inhibition of EZH2 and MEN1 effectively inhibited their proliferation." (PMID 38506728, 2024). "GSK126 was more than 1000 times more selective for EZH2 compared to other methyltransferases and significantly inhibited cell proliferation in diffuse large B-cell lymphoma cell lines harboring Y641F, Y641N, or A677G EZH2 mutations." (PMID 37268997, 2023). "Chromatin writers and erasers are frequently mutated in GC-derived lymphomas, mostly in diffuse large B cell lymphomas (DLBCLs) that show prevalent mutations in major epigenetic modifiers such as EZH2, EP300, CREBBP and KMT2D." (PMID 35580618, 2022). "More recently, Neves Filho and colleagues demonstrated that EZH2 was up-regulated by Myc and associated with high proliferation tumors in diffuse large-B-cell lymphoma." (PMID 34573332, 2021). "The human diffuse large B-cell lymphoma cell line Karpas-422, which harbors an EZH2 gain-of-function mutation (Y641N) and is sensitive to EZH2 inhibition, was used as a control." (PMID 26755663, 2016). "Recurrent, somatic mutations in EZH2, which alter its substrate specificity and increase global H3K27me3 levels, have been found in diffuse large B-cell lymphoma, follicular lymphoma and melanoma." (PMID 27875550, 2016). "Heterozygous gain-of-function mutations in EZH2 are found in follicular lymphoma and diffuse large cell B-cell lymphoma, in which the mutant enzyme is proposed to cooperate with its wild-type counterpart to increase the levels of H3K27me3." (PMID 26637281, 2015). "Overexpression of EZH2 has been detected in various epithelial malignancies, and, more recently, activating mutations of EZH2 have been found in diffuse large B cell lymphoma." (PMID 24778653, 2014). "Furthermore, EZH2 mutations are found in a small percentage of diffuse large B-cell lymphomas, which increases H3K27me3 levels." (PMID 37062547, 2023). "Moreover, EZH2 mutations are found in a small percentage of diffuse large B-cell lymphomas, which increases H3K27me3 levels." (PMID 37062547, 2023). "We further investigate the impact of PRC2 and H3K27 methylation on regulating the binding of the MLL–MEN1 complex and determine the therapeutic implication of this crosstalk in the context of diffuse large B-cell lymphomas (DLBCLs) harboring gain-of-function EZH2 mutations." (PMID 37460547, 2023). "Also, in B-cell-lymphoma patients, EZH2 mutations occur with a frequency of approximately 15-20 percent in either tumor type, particularly in diffuse large-B cell-lymphomas and follicular lymphomas." (PMID 33312959, 2020). "In addition, hotspot mutations that activate EZH2 (e.g. Y641, A677, A687) have now been identified in hematological tumor types (including diffuse large B-cell lymphoma (DLBCL) and follicular lymphoma (up to 25%))." (PMID 25671303, 2015). "It induced a loss of H3K27me3 in mutant and WT EZH2 diffuse large B-cell lymphoma (DLBCL) lines at concentrations from 7–252 nM." (PMID 34458810, 2021). "For example, monoallelic missense mutations of Tyr641 and Ala677 residues of EZH2 occur in more than 22% of diffuse large B-cell lymphoma (DLBCL) and follicular lymphoma." (PMID 28758948, 2017). "A recurrent mutation of tyrosine 641 (Y641) within the EZH2 SET domain has been detected in approximately 22% of diffuse large B-cell lymphoma (DLBCL) and 7% of follicular lymphomas (FL)." (PMID 27329599, 2016). "Gain-of-function mutations in the catalytic site of EZH2 (Enhancer of Zeste Homologue 2), is observed in about 22% of diffuse large B-cell lymphoma (DLBCL) cases." (PMID 25605023, 2015). "In diffuse large-B-cell lymphoma (DLBCL), ctDNA facilitates non-invasive genotyping by identifying hallmark mutations (e.g., MYD88, CD79B, EZH2), enabling molecular cluster classification." (PMID 40430009, 2025).
diffuse large B-cell lymphoma (continued). "For example, EZH2 acts as an oncogene in diffuse large B-cell lymphoma but displays tumor-suppressive properties in myeloid malignancies." (PMID 41392978, 2025). "In diffuse large B-cell lymphoma, histiocytic and dendritic cell neoplasms, the pERK signaling cascade significantly correlated with EZH2 expression." (PMID 38339397, 2024). "In diffuse large B-cell lymphoma, EZH2 is involved in tumor suppressor gene silencing through its H3K27 histone methyltransferase activity." (PMID 38339397, 2024). "More targeted efforts have produced potent inhibitors like EPZ005687 and GSK126, which selectively block EZH2 and halt cell growth in Diffuse Large B-Cell Lymphoma (DLBCL)." (PMID 39766049, 2024). "UNC1999 showed high efficacy in vitro against wild-type and mutant EZH2 and EZH1, effectively reducing the level of H3K27me3 in cells and selectively killing diffuse large B-cell lymphoma cell lines containing EZH2Y641N mutation with low cytotoxicity." (PMID 36672374, 2023). "The “hotspot” gain-of-function mutations at Y641 (Y641X, X = F, N, C, S, or H) within the catalytic domain of EZH2 were found in 22% of patients with GCB-type diffuse large B-cell lymphoma (DLBCL) and 7% of patients with follicular lymphomas." (PMID 37051671, 2023). "Although these compounds have been shown to specifically degrade EZH2 in a few malignancies like triple negative breast cancer and diffuse large B cell lymphoma, few report has indicated their effectiveness in ENKTL." (PMID 38031139, 2023). "Overexpression or gain-of-function mutations of EZH2 have been significantly associated with tumor cell proliferation of triple-negative breast cancer (TNBC) and diffuse large B-cell lymphoma (DLBCL)." (PMID 36642705, 2023). "To investigate whether MENi could also target tumour-intrinsic PRC2 dependence, we evaluated the effects of VTP50469 on the survival of diffuse large B-cell lymphoma (DLBCL) cell lines harbouring gain-of-function mutations in EZH2." (PMID 36635503, 2023). "In diffuse large B-cell lymphoma (DLBCL), EZH2 and GNA13 variants are observed exclusively in the germinal center B-cell subtype, whereas CARD11, MYD88, and CD79B variants are characteristic of the activated B-cell subtype." (PMID 37601650, 2023). "In diffuse large B cell lymphoma (DLBCL) with EZH2Y641 mutation, treatment with an EZH2 inhibitor reduced H3K27me3 in the promoter region of NLRC5, resulting in increased NLRC5 and MHC-I expression." (PMID 35343573, 2022). "On the contrary, in large diffuse B cells lymphoma, IRE1α expression is reduced through a mechanism involving the histone methyltransferase, EZH2 (Enhancer of Zeste Homolog 2)." (PMID 33573353, 2021). "Similar findings were observed in diffuse large B cell lymphoma (DLBCL) where EZH2 inhibition restored MHC expression in DLBCL cell lines." (PMID 33859645, 2021). "In the current study, a combination of pomalidomide and GSK126 synergistically inhibited the growth of EZH2 gain-of-function mutant Diffuse large B-cell lymphoma (DLBCL) cells." (PMID 32906688, 2020). "Oncogenic BCL6 and EZH2 cooperated to accelerate diffuse large B cell lymphoma (DLBCL) development when chronically challenged with SRBCs." (PMID 32695674, 2020). "GSK126 inhibits proliferation of EZH2-mutant diffuse large B cell lymphoma (DLBCL) cell lines and mouse xenografts." (PMID 30466474, 2018). "CPI-169 represses EZH2 activity by reducing histone H3K27me3 to suppress cancer progression in germinal center B-cell-like diffuse large B cell lymphoma (GCB-DLBCL)." (PMID 28561778, 2017). "El1 also exhibited an antitumor effect only in SMARCB1-mutant rhabdoid tumors and EZH2-mutant diffuse large B cell lymphoma (DLBCL)." (PMID 28415635, 2017). "Some FDA-approved drugs for the treatment of solid cancers are 5-Aza that target histone deacetylase (HDAC) in metastatic non-small cell lung cancer and inhibitors of EZH2, a subunit of Polycomb repressive complex in diffuse large B cell Lymphoma (DLBCL)." (PMID 27842508, 2016).
diffuse large B-cell lymphoma (continued). "EZH2 is also overexpressed in 100% of Burkitt lymphomas (BL), 87.5% of grade 3 follicular lymphomas (FL) and 85.7% of diffuse large B-cell lymphomas (DLBCL)." (PMID 26497210, 2016). "Enhancer of Zeste Homolog 2 (EZH2) plays an essential epigenetic role in Diffuse Large B Cell Lymphoma (DLBCL) development." (PMID 25762637, 2015). "Furthermore, we analyzed H3K27me3 levels before and after EZH2 mutation in HepG2 and three diffuse large B-cell lymphoma (DLBCL) cell lines (GSE40970), respectively." (PMID 26169043, 2015). "Various heterozygous mutations of EZH2 at tyrosine 641 (Y641) in the SET domain have been found in 22% of germinal center B-cell and diffuse large B-cell lymphoma (DLBCLs) and 7% of follicular lymphoma." (PMID 25520914, 2014). "In diffuse large B-cell lymphoma (DLBCL), where activating mutations in EZH2 occur, EZH2 function is essential during B-cell activation and clonal expansion in the germinal center." (PMID 25255445, 2014). "Similarly, in diffuse large B-cell lymphoma (DLBCL), the response to EZH2 inhibitors often correlates with gain-of-function mutations in EZH2." (PMID 34671561, 2021). "Furthermore, an inhibitor of EZH2 methyltransferase activity, GSK126, resulted in reduction of H3K27 methylation levels in vitro and in vivo, and inhibited growth of EZH2-mutated diffuse large B-cell lymphoma (DLBCL) mouse xenografts and proliferation of EZH2-mutated DLBCL cell lines." (PMID 30159125, 2018). "In a study, diffuse large B-cell lymphoma cell line with a natural sensitivity to EZH2 inhibition were incubated with varying concentrations of EPZ-6438 until drug resistant outgrowth was observed, then a forward genetics platform was used to identify mutations conferring resistance." (PMID 30555699, 2018). "Moreover, in Tyr 641 mutations diffused large B-cell lymphomas cells, EI1 inhibits cell proliferation and induces apoptosis; UNC-1999 inhibits methyltransferase activity of both EZH1 and EZH2." (PMID 28561778, 2017). "Importantly, EZH1 and EZH2 have been identified as candidate oncogenes in diffuse large B cell lymphoma." (PMID 26405815, 2015). "Somatic heterozygous mutations in the active site of the enhancer of zeste homolog 2 (EZH2) are prevalent in diffuse large B-cell lymphoma (DLBCL) and acute myeloid leukemia (AML)." (PMID 37511137, 2023). "But the clinical trial outcomes of GSK126, another EZH2 inhibitor, in patients with diffuse large B-cell lymphoma (DLBCL), follicular lymphoma (FL), multiple myeloma (MM), and other solid tumors were unsatisfactory." (PMID 35432300, 2022). "EZH2 resistance to mutants that facilitated the accumulation of H3K27me3 was detected in a model of diffuse large B-cell lymphoma (DLBCL)." (PMID 36011043, 2022). "GSK126 can inhibit the proliferation of EZH2-mutant diffuse large B-cell lymphoma (DLBCL) cells and markedly inhibit the growth of EZH2-mutant DLBCL xenografts in mice." (PMID 34050894, 2022). "In this study, we treated Burkitt lymphoma (BL) and diffuse large B-cell lymphoma (DLBCL) cell lines with 3-deazaneplanocin—A (DZNep), an indirect EZH2 inhibitor which possesses anticancer properties both in-vitro and in-vivo." (PMID 31419226, 2019). "Their results also revealed that GSK126 effectively inhibited the proliferation of EZH2-mutant diffuse large B-cell lymphoma (DLBCL) cell lines and retarded the growth of EZH2-mutant DLBCL xenografts in mice." (PMID 30984620, 2019). "Interestingly, in diffuse large B-cell lymphoma (DLBCL), approximately 20% of patients bear activating EZH2 mutations, suggesting that PRC2 may have contrasting context-dependent roles in oncogenesis." (PMID 29527516, 2018). "It selectively degraded EED (Dmax = 95%), EZH2 (Dmax = 95%), and SUZ12 (Dmax = 80%), and it was observed that the proliferation of both the EZH2 mutant diffuse large B-cell lymphoma (DLBCL) cell line and the EZH2 wild-type (WT) rhabdoid cancer cell line was effectively suppressed." (PMID 38389844, 2024).